KRT36 (keratin 36)
Synonyms: HHA6; KRTHA6; HA6
Tractability: No criterion of Open Targets' tractability assessment is met for any kind of drug.
Gene: Protein-coding gene on chromosome 17 (41,486,136 to 41,492,546, reverse strand). Ensembl gene ENSG00000126337.
Pathways (Reactome):
Developmental Biology: Formation of the cornified envelope; Keratinization
Gene Ontology:
Molecular function: structural constituent of skin epidermis; structural molecule activity
Biological process: epithelial cell differentiation; intermediate filament organization; morphogenesis of an epithelium; regulation of keratinocyte differentiation
Cellular component: extracellular exosome; keratin filament; cytoskeleton; cytosol; intermediate filament cytoskeleton
Genetic constraint (gnomAD): Loss-of-function variants: 42 observed, 47.11 expected, observed/expected ratio (o/e) 0.89, 90% interval 0.69 to 1.15. The upper end of that interval is the gene's LOEUF score, 1.15, which puts it in group 5 of 6, group 1 being the genes least tolerant of losing a copy. Missense variants: 627 observed, 626.29 expected, observed/expected ratio (o/e) 1, 90% interval 0.94 to 1.07. Synonymous variants: 277 observed, 267.04 expected, observed/expected ratio (o/e) 1.04, 90% interval 0.94 to 1.15.
Homologues: Orthologues: chimpanzee KRT36 (98% identical), macaque KRT36 (96% identical), dog KRT36 (89% identical), pig KRT36 (85% identical), mouse Krt36 (85% identical), rat Krt36 (84% identical), guinea pig KRT36 (80% identical), tropical clawed frog krt34 (44% identical). Paralogues in human: KRT35 (67% identical), KRT32 (63% identical), KRT31 (62% identical), KRT33A (60% identical), KRT33B (60% identical), KRT34 (58% identical), KRT39 (55% identical), KRT40 (54% identical), KRT38 (52% identical), KRT37 (51% identical), KRT14 (50% identical), KRT17 (49% identical), and 56 more.
Diseases named in the same sentence as KRT36 in open-access papers:
KRT36 is named in the same sentence as 3 diseases in open-access papers, as found by Europe PMC text mining. Sharing a sentence is not in itself a finding about the gene and the disease. The quoted sentences say what the papers report.
tumor (2 papers, 2017 to 2025). "The analysis showed that high expression of CCL26 downregulated KRT36, which is a keratin family member previously thought to be inactivated during tongue tumorigenesis, resulting in the loss of epithelial features of tumor cells, and closely associated with the onset of the EMT process." (PMID 39931245, 2025). "CCL26high OSCC had a characteristic of tumor invasive phenotype with upregulated CLDN8/20 and reduced keratin KRT36, which was significantly associated with EMT markers (CDH1, CDH2, VIM, SNAI2)." (PMID 39931245, 2025). "Levels of KRT36 go from very high in normal control tongue tissue to extremely low in tumors, and tumor free tissue showed a big variation in expression with patients having levels comparable to either control tongue or TSCC." (PMID 28038473, 2017). "Furthermore, data indicate a role in tumor development for KRT36, a novel keratin in the development of TSCC." (PMID 28038473, 2017). "Among the top dysregulated genes when comparing control and tumor free tissue were those involved in apoptosis (CIDEC, MUC1, ZBTB16, PRNP, ECT2), immune response (IFI27) and differentiation (KRT36)." (PMID 28038473, 2017). "Results showed KRT36 to be tongue specific and highly expressed in normal tongue but not in normal buccal mucosa or tumor free tissue from floor of the mouth, gingiva and tonsil." (PMID 28038473, 2017).
KRT36 also shares sentences with these, for which no sentence is quoted: chondroblastoma (1 paper); iron-deficiency (1).